IL4 (interleukin 4)
Diseases named in the same sentence as IL4 in open-access papers (continued):
Sharing a sentence is not in itself a finding about the gene and the disease.
bacterial infection (48 papers, 2012 to 2025). "From these, three HTL epitopes were selected based on their conservation across alleles, and ability to induce IL-4 and/or IL-10 cytokines, which are critical in bacterial infections." (PMID 40863232, 2025). "During a bacterial infection, Th2-associated cytokine IL-4, by binding to the IL-4 receptor (IL-4R), can suppress neutrophil recruitment to the site of inflammation." (PMID 39767651, 2024). "In intracellular bacterial infections, IL-4 has been linked to susceptibility and disease progression, allowing Staphylococcus aureus growth." (PMID 38132773, 2023). "The immune response in malnourished children has been shown to be geared towards Th2 activation, resulting in the proliferation of anti-inflammatory cytokines, such as IL-4 and IL-10, which can increase the predisposition to protozoa and bacterial infections." (PMID 37111135, 2023). "A single study reporting diagnostic performance values for IL-4 reported 100% sensitivity, but a specificity of 76.5% to identify bacterial infections." (PMID 27486746, 2016). "It has been suggested that M(IL4)s might predispose to bacterial infection." (PMID 34691050, 2021). "Su3118 also did not significantly change the mRNA level of Cd206 or Cd86 in macrophages in response to bacterial infection or LPS/IL4 treatment." (PMID 41298379, 2025). "In this research, we showed that eosinophils play crucial roles in facilitating the formation of memory CD8+ T cell during bacterial infection via IL-4-mediated inhibition of apoptosis." (PMID 38413575, 2024). "In our longitudinal study, reductions in pro-inflammatory markers (CRP, IL6 and TNFα) and increments in anti-inflammatory markers (IL4) were associated with an improvement in CSDD and MMSE levels in patients recovering from a bacterial infection." (PMID 37762523, 2023). "During inflammatory condition, such as viral or bacterial infection, there comes to a rapid increase of pro-inflammatory markers such as interleukin 4 (il-4), interleukin 6 (il-6), tumor necrosis factor (TNF) and C reactive protein (CRP)." (PMID 35431842, 2022). "Previous studies have demonstrated that the level of IL-4 is elevated in the SF during bacterial infection." (PMID 35356501, 2022). "Naive CD4+ T cells can be differentiated into Th17 cells that produce IL-17, Th1 cells that produce TNF-α and IFN-γ, and Th2 cells that produce IL-4, and during intracellular bacterial infection." (PMID 35663972, 2022). "These discrepancies suggest that IL-10 and IL-4 signaling are differently regulated in response to bacterial infection versus tissue injury or reflect interspecies differences." (PMID 36127326, 2022). "The effect of IL-4 in neutrophil counts and migration has been highlighted during bacterial infections." (PMID 35154068, 2021). "During bacterial infection, basophil-derived IL-4 promotes the switch of Ly6Chigh monocyte-derived macrophages to anti-inflammatory monocyte-derived macrophages, thereby resolving inflammation and restoring tissue homeostasis in the liver." (PMID 34691073, 2021). "MC-dependent inhibition of phagocytosis has already been described during bacterial infections and appear to be mediated by a quick release of IL-4 from MCs upon bacterial encounter." (PMID 30555491, 2018). "Conversely, IL-4 DCs responded more to molecules involved in bacterial infection, such as flagellin (s=0.27), MDP (s=0.14), TNFα (s=0.39) or IL-1β (s=0.45)." (PMID 25335753, 2014). "In contrast, c-di-GMP treatment reversed the induction of IL-4 production after bacterial infection." (PMID 25333720, 2014). "Reductions in proinflammatory markers C-Reactive protein (CRP), interleukin – 6 (IL6) and tumor necrosis factor-α (TNFα) and increments in anti-inflammatory markers (interleukin – 4 (IL4)) were associated with an improvement in CSDD and MSEE in patients recovering from a bacterial infection." (PMID 37762523, 2023).
bacterial infection (continued). "Additionally, it is also noteworthy that HPV infection modulates the immunological response towards a predominance of Th2-type response (IL-4, IL-5, IL-10, and IL-13), which favors persistence of bacterial infection." (PMID 36897879, 2023). "Interleukin-4 (IL-4) and polymorphonuclear cell (neutrophil) count in the synovial fluid are crucial in mediating local inflammation during bacterial infections and could be valuable biomarkers for PJI." (PMID 35356501, 2022). "In addition, IL-4 affects the function of neutrophils, which are the first line of defense in fighting bacterial infections." (PMID 36211337, 2022). "However, pDCs induced a prominent Th2-like profile compared with CD11c+ DCs (higher secretion of IL-4, IL-5, and IL-10), suggesting different contributions to immune regulation in the context of bacterial infection." (PMID 31017904, 2019). "In addition, since basophil-derived IL4 can promote tissue repair following liver damage induced by bacterial infections, we examined whether α-GalCer pretreatment induces IL4 expression by basophils." (PMID 39355237, 2024). "Nevertheless, having confirmed the anti-colitic effect of the M(IL4)s used here, the murine M(IL4) was found to reduce the severity of inflammation induced by C. rodentium, suggesting that susceptibility to bacterial infection need not be a significant side effect of M(IL4) therapy." (PMID 34691050, 2021). "Spleen levels of IL-4, TNF-α, and IFN-γ play a vital role in immune regulation, host defense against bacterial pathogens and protection from lethal bacterial infection." (PMID 37779705, 2023). "We suspect that the decrease in IL-4 levels after bacterial challenge, except in PBS control group, is due to the suppression of Th2 cell responses after bacterial infection." (PMID 34938794, 2021). "We speculate that the reason why the expression levels of IL-17A increased so much in the spleen is due to the mode of bacterial infection, where V. anguillarum in the earliest phase is sequestered by the spleen and may induce a local immune response similar to the expression pattern of IL-4/13." (PMID 32326041, 2020). "Apart from IFN-γ, IL-4 and IL-10, there are several cytokines, such as IL-12, IL-2, IL-1, IL-18 and TNF-α that are involved in the regulation of immune responses to bacterial infections." (PMID 26619346, 2015). "IL-4 can promote the proliferation and type transformation of B lymphocytes, and IFN-γ affects the immune function in piglets and defends against viral and bacterial infections." (PMID 40431582, 2025). "IL-2and IL-4 are involved in regulating immune response reactions, playing important roles in host cellular and humoral immunity, respectively; IFN-γ plays a key role in defending against intracellular bacterial infections." (PMID 38903796, 2024). "However, high circulating levels of allergy pathway cytokines (IL-13, IL-4), a prominent feature in severe SARS-CoV-2 infection, are uncommon in most bacterial infections." (PMID 37040185, 2023). "Another important aspect of phage’s potential to combat the negative effects of bacterial infection is to stimulate the release of IL-4." (PMID 36211337, 2022). "Conversely, the role of interleukin-4 (IL-4) is more intricate, as it may inhibit Th1 cell activation under certain conditions, potentially exerting a negative impact on the immune response to bacterial infections." (PMID 40332240, 2025). "Bacterial infection had a negative effect on the expression of IL-4/13 paralogues in vivo." (PMID 26870894, 2016).
immune diseases (47 papers, 2005 to 2025). "In the context of IBD, which is closely linked to immune disorders and excessive M1 macrophage activation, the M2-polarizing effect of interleukin-4 (IL-4) plays a crucial therapeutic role." (PMID 39845796, 2024). "Children born after fresh embryo transfer exhibit an increased risk of immune dysfunction in childhood, manifested by elevated Interleukin-4 (IL-4) serum levels and decreased IFN-ɣ/IL-4 ratio." (PMID 37686370, 2023). "Imbalances in IL-4, IL-10 and IL-13 levels can cause immune dysfunction, causing APOs." (PMID 41394354, 2025). "Compared to the CTX group, the serum levels of anti-inflammatory cytokines, including IL-4 and IL-10, were significantly increased in the 2FGF-H group (p < 0.05), suggesting that 2FGF may reverse immune disorders caused by CTX." (PMID 39458546, 2024). "Additionally, Abbas and Vadesilho reported that the increased IL-4 production could cause an abnormal increase of the ratio of IgG1/IgG2, which in turn polarized the offspring immune system toward immune diseases." (PMID 29212186, 2017). "YY2 is also involved in the response to immune diseases, regulating the promoter activity of interleukin 4 (IL-4) by exerting an antagonistic effect that opposes the effect of YY1." (PMID 35457117, 2022). "Children born after fresh embryo transfer via ART displayed a higher risk of immune dysfunction in childhood manifested as elevated plasma IFN-γ and IL-4 levels and decreased ratio of IFN-γ to IL-4." (PMID 34836513, 2021). "CD is characterized as a Th1-mediated inflammatory response with overproduction of interferon-γ (IFN-γ) and TNF-α whereas UC is considered a Th2-mediated immune disease with massive production of interleukin IL-4, IL-5, IL-9, and IL-13." (PMID 30150894, 2018). "NKT cells, a heterogeneous group of T lymphocytes, are known to functionally bridge the innate and adaptive immune system in various immune diseases due to their cytotoxic function and production of the proinflammatory factors IL-4 and IFN-γ." (PMID 27107963, 2016). "IL-4 is produced by activated T cells, and is involved in inflammation, fibrosis, and multiple immune diseases." (PMID 19513121, 2009). "The reduced levels of IL-4 and IL-6 and phosphorylation of p38, IκB-α, and p65 in the jejunum further confirmed that FMS reduced the immune disorder that might be caused by antigenic proteins." (PMID 32047057, 2020). "Moreover, the PCE offspring showed immune disorders after immunization, manifesting as increased IgG1/IgG2a ratio and IL-4 production in the serum." (PMID 29062003, 2017). "Our data demonstrate that direct engagement of TLR4, expressed on the cell surface and localized in the early endosome, enhances IFN-γ production and reduces IL-4 production by iNKT cells, which modulates immune responses in various iNKT cell-mediated immune diseases." (PMID 23028952, 2012). "Taken together, we propose a novel direct activation pathway of iNKT cells in the presence of TCR signals via endogenous or exogenous ligand-mediated engagement of TLR4 in iNKT cells, which regulates immune diseases by altering IFN-γ and IL-4 production." (PMID 23028952, 2012). "Recent studies have shown that KDM7C regulates interleukin 4 production in CD4+ T cells and may play a role in the development of immune diseases and that it directly destabilises SREBP1c and reduces SREBP1c‐dependent lipogenesis." (PMID 39643939, 2024). "It is well known that IFN-γ, IL-4/IL-5/IL-13 and IL-17 are pro-inflammatory cytokines expressed or secreted by activated Th1, Th2 and TH17 cells, respectively, and play key roles in various immune diseases." (PMID 38664707, 2024). "Altogether, our data indicate elevated contents of inflammatory cytokines TNF-α, IL-4, IL-21, BAFF, IL-31, IL-5 and APRIL in CSF samples from ASD patients, suggesting the potential inflammatory conditions and immune dysfunctions that might contribute the pathogenesis and progression of this disease." (PMID 38114596, 2023).
immune diseases (continued). "In addition, the occurrence of immune dysfunction seems to be regulated by IFN-γ and IL-4 levels, and the decrease of their levels may lead to impaired immune function." (PMID 37429891, 2023). "The atypical response to IL-4 in the AFF macrophages may provide a clue that there could be different types of immune dysfunction involved in affective versus non-affective psychotic disorders." (PMID 33716670, 2021). "Unlike usual immunotherapies for immune diseases, venom therapy not only induces a rapid shift in cytokine expression from Th2 (IL-4) to Th1 (IFN-γ) cytokines, but also leads to increased production of immunosuppressive cytokine IL-10 during the initial phase of the treatment." (PMID 26825274, 2016). "To investigate whether TLR4-mediated differential production of IL-4 and IFN-γ by iNKT cells regulates iNKT cell-mediated immune diseases, we compared joint inflammation in CD1d−/− mice adoptively transferred with either WT or TLR4-deficient iNKT cells in the K/BxN serum transfer model." (PMID 23028952, 2012).
infectious disease (26 papers, 2007 to 2026). A disorder directly resulting from the presence and activity of a microbial, viral, or parasitic agent in humans. "While the diagnostic and therapeutic potential of IL-4 in infectious diseases is promising, further research and clinical research are required to fully evaluate its role and optimize treatment strategies." (PMID 38251210, 2024). "As our understanding of IL-4-mediated immune responses continues to evolve, harnessing the diagnostic and therapeutic potential of IL-4 may lead to more effective management of infectious diseases, ultimately improving patient outcomes." (PMID 38251210, 2024). "This study suggests HEBP’s potential in fish nutrition for use as a feed additive and in improving fish health management against infectious diseases by intensifying the immune responses of IL-4 and IL-10." (PMID 39185043, 2024). "IL-10 and IL-4 are common anti-inflammatory cytokines, playing a crucial part in mediating humoral immune response, infectious disease, etc.." (PMID 38998101, 2024). "ARG1 is expressed by macrophages, and downregulates immunosuppressive cytokine production (e.g., IL-4, IL-5, and IL-13) by T-helper cell 2 (Th2) in response to infectious disease." (PMID 35008799, 2021). "Since IFNα-MoDC has the capacity to cross-present antigen to CD8+ T cells, in contrast to IL-4-MoDC, there is growing interest in the use of IFNα-MoDC to treat tumors and infectious diseases." (PMID 30344938, 2018). "Interleukin-4 (IL-4) has therapeutic effects on various injuries and infectious diseases." (PMID 41471264, 2025). "Therapeutic targeting of IL-4 has shown promise in infectious diseases." (PMID 38251210, 2024). "In infectious diseases, blocking IL-4 signaling may have therapeutic benefits by modulating immune responses and reducing inflammation." (PMID 38251210, 2024). "Therefore, measurement of the level of IL‐4 in people with Brucella infections and its comparison with healthy people can increase our knowledge about the reactions of the immune system to this infectious disease." (PMID 32100374, 2020). "Another candidate, IL4R, encoding the alpha chain of the interleukin-4 receptor that can bind IL4 and IL13, has not been previously reported to be associated with infectious diseases." (PMID 37033939, 2023). "White blood cells, lymphocytes and elevated levels of IL-2, IL-4, and IL-6 were also noticed in the mice in CpG-CNP group, indicating that CpG-CNP can serve as an effective adjuvant in order to improve the immune protection and resistance of porcine against infectious diseases." (PMID 32316990, 2020). "Thus, type I IFNs should be added to the long list of cytokines (IL-1β, IL-4, IL-6, IL-15, IL-21) and members of the tumor necrosis factor superfamily (TNFSF) (GITR-L, 4-1BB-L, OX40-L and TNF-α) that are purported to decrease Treg suppressive function in autoimmune and infectious disease models." (PMID 29672594, 2018).
cardiovascular disease (20 papers, 2017 to 2026). "A previous study has demonstrated that high Th2 and IL-4 levels are associated with a reduced risk of cardiovascular disease in healthy subjects, indicating a protective role of Th2 response in cardiovascular disease." (PMID 28757677, 2017). "Other enriched biological mechanisms were energy metabolism and angiogenesis—which may be related to water loss, blood pressure, cardiovascular disease, and IL4 biosynthesis groups of pathways." (PMID 30565091, 2019). "With the capacity to activate both the type I and type II IL-4 receptor, leading to downstream signalling associated with enhanced NADPH oxidase activity, IL-4 may serve as a greater stimulus for macrophage ROS generation than IL-13 in the setting of cardiovascular disease." (PMID 37949903, 2023). "The present study has the potential to inform on more selective targeting of IL-4 and IL-13 and their downstream effector molecules in cardiovascular disease." (PMID 37949903, 2023). "In cardiovascular disease, pathological and protective roles are reported for the Th2 cytokines IL-4 and IL-13, respectively." (PMID 37949903, 2023). "MSC-dependent polarization toward the M2 phenotype in a pro-inflammatory microenvironment and toward the regulatory M2b phenotype in the presence of anti-inflammatory IL-4 should be considered for future therapeutic approaches to treat cardiovascular diseases." (PMID 30359316, 2018). "With this in mind, we wished to determine whether NOX2-derived ROS may be more prevalent in M2 macrophages polarised with IL-4, as compared to IL-13 and thus, be involved in the potentially opposing roles of these cytokines in cardiovascular disease." (PMID 37949903, 2023). "Future studies should focus on a direct comparison of IL-4 and IL-13 as well as their cytokine-specific receptor subunits (i.e., IL-2Rγ and IL-13Rα1, respectively) in the context of cardiovascular disease in vivo to validate the therapeutic potential of targeting one cytokine over the other." (PMID 37949903, 2023). "Taken together, these findings suggest that despite both promoting a M2 phenotype, IL-4 and IL-13 may play opposing roles in cardiovascular disease." (PMID 37949903, 2023). "Given the central inflammatory role that macrophages play in cardiovascular disease, we hypothesised that the opposing effects of IL-4 and IL-13 may be via their differential modulation of M2 macrophage function, specifically the release of ROS." (PMID 37949903, 2023). "The similar actions of IL-4 and IL-13 on M1 and M2 macrophages suggests that the opposing roles of these cytokines in cardiovascular disease may be via effects on other cell types." (PMID 37949903, 2023). "On the other hand, the analysis of a cohort of patients with severe CVD (cardiovascular disease) detailed that the concentration of IL-4 and IL-17 in severe disease decreased comparing patients with mild CVD and non-CVD; suggesting a protective effect of these cytokines." (PMID 36860987, 2023). "Treg, with the secretion of anti-inflammatory IL-4, IL-10, and TGF-β, has been generally recognized as the crucial CD4+ T cell for the balance of systemic inflammation and relevant cardiovascular diseases." (PMID 36678161, 2023). "Overall, this study did not identify major differences in the ability of IL-4 and IL-13 to modulate macrophage function, suggesting that the opposing roles of these cytokines in cardiovascular disease are likely to be via actions on other cell types." (PMID 37949903, 2023).